EPHX1 (epoxide hydrolase 1)
Description:
Biotransformation enzyme that catalyzes the hydrolysis of arene and aliphatic epoxides to less reactive and more water soluble dihydrodiols by the trans addition of water (By similarity). Plays a role in the metabolism of endogenous lipids such as epoxide-containing fatty acids. Metabolizes the abundant endocannabinoid 2-arachidonoylglycerol (2-AG) to free arachidonic acid (AA) and glycerol. Binds 20(S)-hydroxycholesterol (20(S)-OHC) (By similarity).
Synonyms: mEH; EPHX; EPOX; HYL1
Tractability: Small molecule: a high-quality ligand is known. Antibody: UniProt predicts a signal peptide or a membrane-spanning region. PROTAC: ubiquitination databases record sites on it; its protein half-life has been measured; a small molecule that binds it is known.
Target class: Enzyme; Serine protease S33 family; Serine protease SC clan; Serine protease; Protease
Safety:
Unwanted effects reported when the protein is acted on. In parentheses: how it was acted on, where the effect was seen, and who reports it.
craniofacial abnormality (source: ClinPGx)
grade 1-4 nephrotoxicity (source: ClinPGx)
have a child with a craniofacial abnormality (source: ClinPGx)
having a child with a craniofacial abnormality (source: ClinPGx)
nephrotoxicity (source: ClinPGx)
Gene: Protein-coding gene on chromosome 1 (225,810,095 to 225,845,567, forward strand). Ensembl gene ENSG00000143819.
Subcellular location: Microsome membrane; Endoplasmic reticulum membrane
Pathways (Reactome):
Metabolism: Phase I - Functionalization of compounds
Gene Ontology:
Molecular function: cis-stilbene-oxide hydrolase activity; epoxide hydrolase activity; protein binding; oxysterol binding; catalytic activity; ether hydrolase activity
Biological process: arachidonate metabolic process; epoxide metabolic process; xenobiotic metabolic process
Cellular component: endoplasmic reticulum membrane
Genetic constraint (gnomAD): Loss-of-function variants: 41 observed, 48.35 expected, observed/expected ratio (o/e) 0.85, 90% interval 0.66 to 1.1. The upper end of that interval is the gene's LOEUF score, 1.1, which puts it in group 4 of 6, group 1 being the genes least tolerant of losing a copy. Missense variants: 550 observed, 599.52 expected, observed/expected ratio (o/e) 0.92, 90% interval 0.86 to 0.98. Synonymous variants: 221 observed, 238.67 expected, observed/expected ratio (o/e) 0.93, 90% interval 0.83 to 1.03.
Gene-disease validity (ClinGen):
ClinGen rates the evidence that EPHX1 causes each of these diseases.
hereditary nonpolyposis colon cancer (autosomal dominant): Limited.
Homologues: Orthologues: chimpanzee EPHX1 (99% identical), macaque EPHX1 (89% identical), pig EPHX1 (85% identical), dog EPHX1 (85% identical), guinea pig EPHX1 (85% identical), rat Ephx1 (84% identical), rabbit EPHX1 (84% identical), mouse Ephx1 (84% identical), zebrafish ephx1 (62% identical), tropical clawed frog ephx1 (56% identical), Caenorhabditis elegans W01A11.1 (45% identical), Drosophila melanogaster Jheh1 (40% identical), and 36 more.
Diseases named in the same sentence as EPHX1 in open-access papers:
EPHX1 is named in the same sentence as 86 diseases in open-access papers, as found by Europe PMC text mining. Sharing a sentence is not in itself a finding about the gene and the disease. The quoted sentences say what the papers report.
lung carcinoma (19 papers, 2000 to 2025). "Significant association between early-onset lung cancer and the EPHX1 exon 4 variant (OR = 3.33, 95% CI = 1.50–7.41)." (PMID 40958859, 2025). "Both EPHX1 polymorphisms in Tyr113His and His139Arg revealed significantly high risks in developing lung cancer and polycystic ovary syndrome." (PMID 26295053, 2015). "CYP1A1*2A and EPHX1 His139Arg polymorphisms were associated with increased risk to lung cancer in dominant genetic model, whereas EPHX1 Tyr113His and SULT1A1 Arg213His imparted reduced risk in recessive genetic model." (PMID 22206016, 2011). "Polymorphisms at exons 3 and 4 of the EPHX1 gene have been associated with variation in EPHX1 activity and a low-activity genotype of EPHX1 gene was associated with decreased risk of lung cancer among whites." (PMID 20689807, 2010). "Two haplotypes in EPHX1 were significantly associated with lung cancer risk in the overall population." (PMID 19479063, 2009). "Two haplotypes in EPHX1 compared to all other haplotypes were significantly associated with lung cancer in the overall population and in adenocarcinoma cases only: TGGCACTC as a risk factor and CGGCGCCT as a protective factor." (PMID 19479063, 2009). "In particular, EPHX1 rs2234922 has been previously associated both with risk and with protection for lung cancer." (PMID 19479063, 2009). "Microsomal epoxide hydrolase (EPHX1) has a putative dual function for enzyme activity which possibly modifies lung cancer risk." (PMID 18298806, 2008). "Individually, CYP1A1*2A polymorphism was significantly associated with increased lung cancer risk (OR = 1.69;95%CI = 1.11–2.59,p = 0.01), whereas EPHX1 Tyr113His and SULT1A1 Arg213His conferred reduced risk (OR = 0.40;95%CI = 0.25–0.65,p<0.001 and OR = 0.51;95%CI = 0.33–0.78,p = 0.002 respectively)." (PMID 22206016, 2011). "For example, the significant association between haplotypes in EPHX1 and lung cancer risk emphasizes that the effect of multiple SNPs may be important despite null associations in single SNP analyses, and should be taken into consideration in GWAS." (PMID 19479063, 2009). "However, this study provides some support for the T-Allel of GPX1(Pro200Leu) and the C-Allele of EPHX1(His113Tyr) to play a protective role in early onset lung cancer susceptibility." (PMID 18298806, 2008). "The low variety of EPHX1 genotypes may reduce the risk of lung cancer." (PMID 37965333, 2023). "EPHX1 plays significant roles in the detoxification and activation of tobacco-derived carcinogens, as well as lung cancer, and the low activity genotype of EPHX1 gene is related to the reduction of lung cancer risk in whites." (PMID 36072012, 2022). "EPHX1 overexpression has been observed in other human malignancies, including liver cancer, lung cancer, and breast cancer." (PMID 34881229, 2021). "To further analyze possible effects of the EPHX1 and CYP1A1 SNPs, we estimated their haplotype frequencies and risk imparted towards lung cancer." (PMID 22206016, 2011). "In smokers, EPHX1 Tyr113His and SULT1A1 Arg213His polymorphisms reduced the risk of lung cancer, whereas CYP1A1*2A, CYP1A1*2C and GSTP1 Ile105Val imparted increased risk in non-smokers only." (PMID 22206016, 2011). "EPHX1 has been reported to be related to liver cancer and to play an important role in the development of a variety of tumors, such as liver cancer, lung cancer, and breast cancer." (PMID 34881229, 2021). "Distribution of CYP1A1 and EPHX1 haplotype frequency among lung cancer cases and controls." (PMID 22206016, 2011). "Our data do not support proposed associations between lung cancer and EPHX1 rs2234922, CYP1B1 rs1800440, and MPO rs2333227." (PMID 19479063, 2009). "We included 8 SNPs from EPHX1 gene, 7 of which not previously studied in association with lung cancer." (PMID 19479063, 2009). "In this large population-based case-control study of lung cancer we have observed that EPHX1, CYP1A1, CYP1B1 and CYP2A6 genes may play a role in lung cancer susceptibility." (PMID 19479063, 2009).
lung carcinoma (continued). "MDR analysis identified two distinct predictor models for the risk of lung cancer in smokers (tobacco chewing, EPHX1 Tyr113His, and SULT1A1 Arg213His) and non-smokers (CYP1A1*2A, GSTP1 Ile105Val and SULT1A1 Arg213His) with testing balance accuracy (TBA) of 0.6436 and 0.6677 respectively." (PMID 22206016, 2011). "Concluding our investigation, qRT-PCR experiments confirmed the heightened expression levels of EPHX1, LDHA, SHC1, MYO6, and TLE1 in lung cancer cell lines." (PMID 37965333, 2023).
asthma (12 papers, 2008 to 2025). "Binary logistic regression analysis of associations between SNPs of GSTP1, HMOX1, CAT, EPHX1 gene and asthma." (PMID 40433469, 2025). "The genotype combinations GSTT1 ∗ GSTP1 rs762803 and GSTM1 ∗ EPHX1 rs2854450 were also associated with diisocyanate-induced asthma." (PMID 35186174, 2022). "A case-control study demonstrated that genetic variants of antioxidant defense genes, SOD2, GST, and EPHX1, were associated with increased susceptibility to diisocyanate-induced asthma." (PMID 28208751, 2017). "Age-stratified analysis of associations between SNPs of GSTP1, HMOX1, CAT, EPHX1 gene and asthma." (PMID 40433469, 2025). "Given EPHX1's crucial role in metabolizing polycyclic aromatic hydrocarbons, its genetic variants may demonstrate more pronounced effects on asthma susceptibility in populations with significant airborne pollutant exposure." (PMID 40433469, 2025). "Notably, the EPHX1 Y113H genotypes did show the association with asthma risk in single-locus analysis performed in our previous study (P = 0.21df = 2)." (PMID 24895604, 2014). "A recently published study also showed that children with GSTP1 Val/Val genotype and a high activity for EPHX1 (microsomal epoxide hydrolase, also part of the antioxidative system) were at the highest asthma risk, especially if they lived < 75 m from a major road." (PMID 18709160, 2008). "Previous studies have demonstrated that genes involved in oxidative stress response, including GSTP1, CAT, HMOX1, and EPHX1, participate in the pathogenesis of asthma." (PMID 40433469, 2025). "The epoxide hydroxylase (EPHX1) and glutathione S-transferase (GST) genetic variants are associated with an increased risk for lifetime asthma." (PMID 22355322, 2012). "When stratified according to proximity to pulp and paper industries there were also two haplotype blocks located in two genes (EPHX1 and GSTP1) that were associated to asthma before correction." (PMID 23066387, 2012). "In particular, three ADE genes, which can be considered common susceptibility genes to asthma, such as glutathione-disulfide reductase (GSR), EPHX1, and GPX1, highlighted a relevant interaction in both variants of asthma in men and women (except for the GPX1 gene in nonallergic asthma in women)." (PMID 41154690, 2025). "Interestingly, the EPHX1 Y113H and IL5 C-703T genes showed an antagonistic character of gene-gene interactions exclusively in women with both pathogenetic variants of asthma." (PMID 24895604, 2014). "EPHX1 and GSTP1 variants affect the risk of asthma in children exposed to traffic exhaust." (PMID 19371435, 2009). "Genetic model distributions of HMOX1 gene rs2071747, CAT gene rs1049982, EPHX1 gene rs41266231, rs1051740, rs2234922 did not significantly differ between the asthma group and the control group." (PMID 40433469, 2025). "In particular, three ADE genes such as GSR, EPHX1, and GPX1 showed significant interaction in both variants of asthma in both men and women (except for the GPX1 gene in nonallergic asthma in women); therefore, they can be considered as common susceptibility genes to asthma." (PMID 24895604, 2014). "In nonallergic asthma, the smallest significance levels appeared for 5 SNPs (the GCLM −588C>T, GSR T>C, CAT −21A>T, CYBA −930A>G, and EPHX1 Y113H) in men and for 2 SNPs (the EPHX1 Y113H and GPX2 G>A) in women." (PMID 24895604, 2014).
hepatocellular carcinoma (7 papers, 2013 to 2025). A malignant tumor that arises from hepatocytes. "Furthermore, it has been demonstrated that EPHX1 causes resistance to 5-fluorouracil in hepatoma cells and promotes chemoresistance in leukemia." (PMID 35967424, 2022). "In hepatocellular carcinoma, LINC00592 was associated with patient prognosis and could target the cold shock domain-containing E1 protein, CDK6, miR-122-5p, and epoxide hydrolase 1, promoting the proliferation of hepatocellular carcinoma cells." (PMID 36050740, 2022). "This study systematically investigates the role and molecular mechanism of EPHX1 in hepatocellular carcinoma (HCC) cell viability, apoptosis, and regorafenib resistance." (PMID 40745342, 2025). "In recently published studies of hepatocellular carcinoma (HCC), LINC00205 was found to interact with miR-122-5p to promote proliferation, migration, and invasion, and with miR-184 to modulate epoxide hydrolase 1 (EPHX1) expression." (PMID 32718068, 2020).
epilepsy (6 papers, 2010 to 2025). A brain disorder characterized by episodes of abnormally increased neuronal discharge resulting in transient episodes of sensory or motor neurological dysfunction, or psychic dysfunction. "Herein, we investigated the association between CBZ-resistant epilepsy, CBZ-sensitive epilepsy and EPHX1 methylation in a northern Han Chinese population, and conducted an analysis of clinical risk factors for CBZ-resistant epilepsy." (PMID 31164100, 2019). "Our study has three key findings: (i) the SCN1A IVS5-91G>A SNP is associated with susceptibility to epilepsy, (ii) SNPs in EPHX1 gene influence CBZ pharmacokinetic and (iii) CBZ plasma level is not an indicator of resistance to the therapy." (PMID 26555147, 2015). "In a recent study of 70 patients with epilepsy in Scotland, a multivariate model incorporating patient age and EPHX1 Try113His and His139Arg polymorphisms, revealed a significant association between the genotypes and the maintenance dose of carbamazepine." (PMID 27713373, 2010). "Methylation levels in EPHX1 promoter associated with CBZ-resistant epilepsy significantly." (PMID 31164100, 2019). "A study of 75 people from northern China, 25 of whom had carbamazepine (CBZ)-resistant epilepsy, showed a significant difference in methylation levels in the promoter of the epoxide hydrolase 1 gene EPHX1 between them, CBZ-sensitive patients and controls." (PMID 34069567, 2021). "We found a significant high EPHX1 methylation level in CBZ-resistant group in northern Han Chinese epilepsy patients." (PMID 31164100, 2019). "The clinical characteristics and EPHX1 methylation of the CBZ-resistant epilepsy patients have been described." (PMID 31164100, 2019). "Herein, we investigated the association between Carbamazepine-resistant (CBZ-resistant) epilepsy and EPHX1 methylation in a northern Han Chinese population, and conducted an analysis of clinical risk factors for CBZ-resistant epilepsy." (PMID 31164100, 2019). "On the other hand, high EPHX1 methylation levels in peripheral blood DNA in CBZ-resistant epilepsy group was also meaningful equally." (PMID 31164100, 2019). "The goal of the study was to determine differential methylation profiles of EPHX1-candidate gene in CBZ-resistant epilepsy." (PMID 31164100, 2019). "Single nucleotide polymorphisms of the microsomal epoxide hydrolase (EPHX1) gene have been shown to affect carbamazepine pharmacokinetics in Chinese people with epilepsy, and in Kosovan people with epilepsy of Albanian ethnicity." (PMID 28082152, 2018). "We found a significant association between EPHX1 methylation and CBZ-resistant epilepsy patients in the northern Han Chinese patients, and EPHX1 methylation may be the potential marker for CBZ resistance prior to the CBZ therapy." (PMID 31164100, 2019). "In summary, although CBZ is the first choice drug for several epilepsy types, genetic variation in CBZ metabolic pathway like EPHX1 methylation contributed, in part, to the differences in patients’ response." (PMID 31164100, 2019). "A retrospective study in Japanese patients with epilepsy implicated the GSTM1 null genotype as a risk factor for carbamazepine-induced mild hepatotoxicity, whereas the EPHX1 polymorphisms did not lead to any elevation of transaminases in 192 Japanese patients treated with carbamazepine." (PMID 27713373, 2010).
preeclampsia (6 papers, 2014 to 2024). Preeclampsia is a hypertensive disorder of pregnancy that is characterized by new-onset hypertension with proteinuria presenting after 20 weeks of gestation, and depending on mild or severe forms may initially present with severe headache, visual disturbances, and hyperreflexia. "EPHX1 mutations have been associated with many types of cancer, including preeclampsia and hypercholesterolemia or increased serum concentration of bile acid." (PMID 38666947, 2024). "More recently, certain polymorphisms of the human mEH gene, EPHX1, have been associated with an increased risk to develop preeclampsia, a severe pregnancy complication, characterized by hypertension." (PMID 28975360, 2017). "Several studies have shown that EPHX1 has an important effect on the female reproduction system and influences susceptibility to spontaneous abortion, ovarian cancer, and preeclampsia." (PMID 24505354, 2014). "The role of EPHX1 on the reproductive function could also be illustrated by the reported link between EPHX1 polymorphisms and spontaneous abortion or preeclampsia." (PMID 34342583, 2021).
breast carcinoma (5 papers, 2008 to 2023). "There is no known association between EPHX1 and breast cancer risk." (PMID 29996894, 2018).
colorectal cancer (5 papers, 2007 to 2025). A primary or metastatic malignant neoplasm that affects the colon or rectum. "The aim of this study is to quantitatively summarize the relationship between EPHX1 polymorphisms and colorectal cancer (CRC) risk." (PMID 22928041, 2012). "Contradictory data have been provided by different studies investigating the EPHX1 codon 113 and EPHX1 codon 139 polymorphisms in relation to the risk of colorectal carcinomas and adenomas." (PMID 18093316, 2007). "Quantitative analyses of the EPHX1 His139Arg polymorphism on the colorectal cancer (CRC) risk." (PMID 22928041, 2012). "Quantitative analyses of the EPHX1 Tyr113His polymorphism on the colorectal cancer (CRC) risk." (PMID 22928041, 2012). "To evaluate if the genetic polymorphisms in GST and EPHX1 modify colorectal carcinoma and adenoma risk in relation to ratio of total meat to total fruit, berry and vegetable intake, we stratified the case groups based on the most common allele or any polymorphic allele." (PMID 18093316, 2007). "It is likely that EPHX1 could modify the association between diet and colorectal carcinoma and adenoma risk." (PMID 18093316, 2007). "In addition the study supports the notion that the biotransformation enzymes GSTM1, GSTP1 and EPHX1 may modify the effect of dietary factors on the risk of developing colorectal carcinoma and adenoma." (PMID 18093316, 2007). "Expressions of EPHX1 and EPHX2 were significantly decreased in CRC and presented as diagnostic and prognostic biomarkers for colorectal cancer." (PMID 41465541, 2025).
ovarian carcinoma (5 papers, 2008 to 2023). A malignant neoplasm originating from the surface ovarian epithelium. "It has been demonstrated that influencing EPHX1 activity or causing its dysregulation may lead to the occurrence of gynecological disorders such as pre-eclampsia, cervical cancer, and ovarian cancer." (PMID 38098472, 2023).
chronic obstructive pulmonary disease (4 papers, 2007 to 2025). A chronic and progressive lung disorder characterized by the loss of elasticity of the bronchial tree and the air sacs, destruction of the air sacs wall, thickening of the bronchial wall, and mucous accumulation in the bronchial tree. "Microsomal epoxide hydrolase (EPHX1) is an enzyme involved in the detoxification the products of smoking and is proposed to be a genetic factor for the development of chronic obstructive pulmonary disease (COPD)." (PMID 23426996, 2013).
esophageal cancer (4 papers, 2011 to 2025). A primary or metastatic malignant neoplasm involving the esophagus. "Noteworthy were results in EPHX1, where frequency of haplotypes among cases was strikingly similar to report published in esophageal cancer from north India." (PMID 22206016, 2011).
Hypertension (4 papers, 2016 to 2025). The presence of chronic increased pressure in the systemic arterial system. "Among them, SNPs in genes Ephx1, Pla2r1, and Ccdc28b were identified as candidates responsible for the concomitant manifestation of hypertension and signs of accelerated aging in OXYS rats." (PMID 32429546, 2020).